BIRC3 (baculoviral IAP repeat containing 3)
Diseases named in the same sentence as BIRC3 in open-access papers (continued):
Sharing a sentence is not in itself a finding about the gene and the disease.
tumor (continued). "In LUAD, increased expression of BIRC3 could promote tumor growth and metastasis." (PMID 36389757, 2022). "Although BIRC3 gene expression data from the TCGA revealed differential yet positive expression of BIRC3 across all subtypes of GBM, the relative contributions of BIRC3 protein expression by the tumor cell niche and vascular microenvironment niche remains unclear." (PMID 28839258, 2017). "BIRC3 expression was highly indicative of immunosuppression within the TME, hindering effective anti-tumor responses." (PMID 40616096, 2025). "Targeting intracellular PD-L1 has been shown to promote antitumor immune responses in some mouse tumor models, and nuclear PD-L1 upregulates several genes involved in immunosuppression, including PDCD1LG2, BIRC3, RELB, and VSIR." (PMID 39996786, 2025). "The interaction between BIRC3, MAP3K14, and the NF-κB pathway highlights the impact of BIRC3 inactivation on tumor cells dependent on this pathway." (PMID 39301019, 2024). "To define the clinical relevance of SQLE-regulated NF-κB signaling and BIRC3 expression, we performed IHC analysis in tumor tissues from CRC patients with anti-SQLE, anti-IκBα and anti-BIRC3 antibodies." (PMID 38762737, 2024). "Activated NF-κB upregulates the expression of baculoviral IAP repeat containing 3 (BIRC3), sustains tumor cell survival after 5-FU treatment and promotes 5-FU resistance of CRC in vivo." (PMID 38762737, 2024). "Notable changes were observed in the expression levels of BIRC3 and BIRC5 across different tumor stages." (PMID 37781078, 2023). "The results indicated that NAIP, BIRC2, BIRC3, XIAP, BIRC5, and BIRC6 showed significantly higher expression levels in tumor tissues than in normal tissues." (PMID 37781078, 2023). "A previous study has found that TNFR2 suppresses the NK cell growth by activating the BIRC3/TRAF1 signaling pathway and promoting the immunosuppressive function of NK cells in the tumor microenvironment." (PMID 35494080, 2022). "It is shown that CLEC7A, VCAN, and KYNU were significantly upregulated in monocytes, BIRC3 and SOD1 were mainly distributed in T cells, CCL20 was highly expressed in tumor cells, and CD69 was highly expressed in B cells." (PMID 35480896, 2022). "To validate BIRC3 modulation of stemness genes in vitro, we further measured relative expression of CD133, ABCG2 and BMP4 using mRNA samples extracted from xenograft tumor tissues." (PMID 35008722, 2021). "Based on CRISPR screen, data mining, and in vivo experiments, we identified and validated three genes (SMAD3, BIRC3, and SLC9A5) able to promote both BRAFi‐resistance and tumor growth." (PMID 33724679, 2021). "Comparison between the pairs of primary and recurrent tumor samples revealed that 5 genes were concordantly upregulated with a > twofold difference in expression level, including BCL10, BIRC3, CD40, TNFRSF10A and TRAF4." (PMID 34488754, 2021). "We observed that the BIRC2, BIRC3, BIRC5, and BIRC7 genes showed the increased levels of expression in tumor tissue compared to normal tissue, while in the case of the BIRC1, BIRC4, BIRC6, and BIRC8 genes, we saw the decreased expression levels." (PMID 33673050, 2021). "Compared to the NCI60 analysis, we further revealed distinct expression pattern of BIRC5 and BIRC7 and synchronized expression for NAIP, BIRC2, BIRC3, XIAP and BIRC6 in multiple tumor types." (PMID 31964418, 2020). "BIRC3, CAV1, CAV2, FN1, ITGA1 and THBS1 were functionally enriched to focal adhesion, which contributes to antiangiogenic and anti-tumour effects." (PMID 27557147, 2016). "The results are also consistent with reduced expression of the antiapoptotic genes Birc3, Birc5 and Nos2 in livers from TLR4-/- mice suggesting that TLR4 mediates survival ligands to tumor initiating cells." (PMID 27391331, 2016). "The tumours highlighted the overexpression of MYB (fold‐change increase = ×2.04), BCL2 (fold‐change increase = ×2.34) and BIRC3 (fold‐change increase = ×3.93)." (PMID 26969893, 2016).
tumor (continued). "Senescent GBM cells not only upregulate BIRC3 but also induce BIRC3 expression and promote radioresistance in non-senescent tumor cells." (PMID 39972068, 2025). "Our findings that TRUB1 knock-down inhibits BIRC3 expression, along with the suppression of TNFα signaling via NFκB, underscore the role of BIRC3 in CRC tumor progression and suggest that TRUB1 may regulate CRC growth through BIRC3-dependent mechanisms." (PMID 40260225, 2025). "Single-cell expression analysis revealed that KRT5 and FABP7 were highly enriched in tumor cells, UGT2B4 was predominantly expressed in epithelial cells, BIRC3 and KLRB1 were enriched in CD8+ T cells, while MRC1 and CD209 were highly expressed in monocytes/macrophages." (PMID 40612672, 2025). "Additionally, hormone deprivation triggered an upregulation of tumor drug resistance genes ABCB11, BIRC3, FGF2 and NRG1." (PMID 40075208, 2025). "BIRC2 and BIRC3 mRNA levels in tumor and paired non-tumor tissues in HNSCC patients were further analyzed." (PMID 39578442, 2024). "To test whether SQLE upregulates BIRC3 expression through NF-κB, we overexpressed HA-RelA, the central transcription factor in NF-κB pathway, in SQLE-depleted tumor cells." (PMID 38762737, 2024). "Notably, iCAFs marked by TPM2 were enriched in the initial differentiation phase while myCAFs characterized by BIRC3, CCT6A, HNRNPF, and ID1 were enriched in the terminal differentiation phase during tumor progression." (PMID 37968457, 2023). "Normal B cells mostly form protein complexes that are independent of LU isoforms and they mediate BIRC3’s tumor-suppressive functions." (PMID 35581194, 2022). "We focused on the top 3 tumor‐promoting genes: SMAD3, BIRC3, and SCL9A5." (PMID 33724679, 2021). "This is likely attributable to the lack of specific ligands for BIRC3, as well as overlooked by its low expression in most tumor cells (detectable in only 8% of 60 tumor cell lines) compared to other IAP proteins, such as cIAP1 and XIAP." (PMID 32718354, 2020). "With the regulation of the tumor microenvironment, more genes were upregulated with over two-fold differences in both HK1 and C17 xenografts after CYLD knockout, including BCL2A1, CXCL1, BIRC3, SERPINB2, total VEGF, TNFA, and VEGFA." (PMID 32708712, 2020). "In addition, PIK3CG and BIRC3 were also found in PPI network and correlated with immune cells infiltrating in tumor microenvironment." (PMID 32010618, 2019). "Our transcriptome sequencing results identified several DEGs involved in cell adhesion, such as BIRC2, BIRC3, and MLCK, which could influence tumor invasion or metastasis." (PMID 28114404, 2017). "BIRC3 mRNA levels were not significantly different between tumor and normal tissues." (PMID 39578442, 2024). "Interestingly, we recovered the tumor‐promoting genes SMAD3, BIRC3, and SLC9A5 identified above." (PMID 33724679, 2021). "However, despite the absence of significant differences in BIRC3 mRNA levels between tumor areas and normal epithelium in the TCGA database (P < 0.0001), high expression levels of cIAP2 were observed specifically in OSCC tumor areas compared to normal epithelium (P < 0.0001)." (PMID 39578442, 2024). "Notably, TRIM31 (logFC = 1.14), ANXA1 (logFC = 1.05), GBP1 (logFC = 1.01), BIRC3 (logFC = 0.99), APOL1 (logFC = 0.97), IL18 (logFC = 0.94), ANXA2 (logFC = 0.89), BHLHE40 (logFC = 0.83), and EPHA2 (logFC = 0.75) exhibited significant upregulation in tumour tissues." (PMID 38254861, 2024). "Due to the relationship between BIRC3, MAP3K14 and the non-canonical NF-kB pathway, BIRC3 inactivation bears consequences also on the tumor cells relying on NF-kB pathway to survive." (PMID 33413657, 2021). "However, when we examined tumor growth over our 5-day course treatment with TMZ, we did not observe any significant statistical difference in tumor size between control U251 GBM xenografts and BIRC3-overexpressing U251 GBM xenografts." (PMID 26888114, 2016).
tumor (continued). "However, the gene‐level integrated analysis revealed heterogeneity in expression, copy number variation and methylation status of MDM4, RRAGC, HERC2, BIRC3 and TSC2 genes within and across individual tumours, suggesting that they may not be ideal biomarkers for PDAC." (PMID 35061935, 2022).
infection (52 papers, 2008 to 2025). The state of being infected such as from the introduction of a foreign agent such as serum, vaccine, antigenic substance or organism. "Both genes are differentially expressed when comparing wt versus LPKO EBV infected B cells 48 h post infection reflecting the loss (BIRC3) and gain (BCL2L11) of intragenic interactions." (PMID 39747661, 2025). "Inhibition of Brd4 or elimination of Brd4-mediated BIRC3 eRNA synthesis suppressed infection-associated apoptosis resistance." (PMID 32820150, 2020). "It is known that BIRC3 transcription is significantly repressed already 48 h after infection of naive B cells with wild-type EBV whereas transcription of BCL2L11 is induced after 24 h to become repressed later starting at day 3 post infection." (PMID 39747661, 2025). "In a mouse model of infection, blocking the Birc3/TLR4/Myd88 signaling pathway showed a protective effect against carbapenem-resistant K. pneumoniae." (PMID 38274787, 2023). "The expression of cell death and apoptosis-associated genes (e.g., BID, BIRC3 and PARP14) increased throughout the infection, suggestive of increased cell death in response to the infection." (PMID 34452468, 2021). "Although the transcription of RIPK1 (a key mediator of necroptosis) was unchanged, its suppressor BIRC3 showed greater transcription in Axl−/− macrophages than in control macrophages after infection." (PMID 32611752, 2020). "It was suggested that infection with Chlamydia protects mammalian host cells against apoptosis via BIRC3 up-regulation." (PMID 24959205, 2014). "In the NOD-like receptor signalling pathway (hsa04621) 10 genes (of a total of 57 pathway genes) were differentially expressed at 4 h post infection and five of them were upregulated more than 10-fold, encoding IL6, IL1B, BIRC3, CXCL1 and CXCL2." (PMID 23326599, 2013). "By inhibiting caspase protease activity, BIRC3 prevents excessive cell death, which may help maintain lactation during infection." (PMID 41252605, 2025). "However, BIRC3 was overexpressed in the early stage of infection (12 h) and repressed in the late stage of infection (48 h)." (PMID 38891754, 2024). "Infection with B19V led to strong downregulation of BIRC3 mRNA levels." (PMID 30845701, 2019). "On the other hand, five genes were down-regulated, that are involved in lipid transport and metabolism (ApoA1, ApoB), apoptosis (Birc3), and blood clotting (coagulation) (Fga, Fgb), potentially indicating an attempt to control lipid accumulation and plaque growth induced by infection." (PMID 26619277, 2015). "Moreover, upregulation of CXCL8 and BIRC3 were rescued by infection of HIV-1 ∆Vpr + Vpr." (PMID 39269169, 2024). "The present RNA-Seq analysis in HRECs further supports a more than twofold increase in the expression of BIRC3 from 6 hpi to 48 hpi, suggesting that SARS-CoV-2 inhibits apoptosis at a very early stage of infection." (PMID 38189329, 2024). "During pathogen infection, BIRC2 and BIRC3 inhibit apoptosis by ubiquitination and promoting proteasomal degradation." (PMID 38891754, 2024). "Differential gene expression analysis revealed a common epithelial host response to mycobacteria, including upregulation of BIRC3, S100A8 and DEFB4, and downregulation of BPIFB1 at 48 h post infection." (PMID 37822359, 2023). "The genes, Ccl2, Ccl20, Csf1, Cx3cl1, Cxcl1, Cxcl3, Il6, Birc3, Map3k8, Nos2, Nfkb2, Tnfrsf1b, and Vcam1, played core roles in a PPI network, and interacted closely with other ones in the infection." (PMID 33042984, 2020). "Genes that were down-regulated genes at 24h post infection included inflammatory and anti-pathogen genes (CSF1 and USP2) and the cell apoptosis and death genes (MICB, BUB1B, ITGB2, UBB and BIRC3)." (PMID 23527143, 2013). "IRAK3, BIRC3 and TNF were dysregulated throughout the entire infection and were classified into the apoptosis pathway." (PMID 21629653, 2011).
infection (continued). "Finally, a large cluster, especially in terms of small RNA regulation upon infection, was “cell proliferation, anti-apoptosis, and oncogenesis,” where EIF2AK2, BIRC3, and TXNIP were significantly upregulated upon infection." (PMID 40510596, 2025). "Infection by H. pylori led to a striking albeit transient up-regulation of BIRC2, BIRC3 and BCL2A1." (PMID 35089437, 2022). "Interestingly, infection with the clinical isolate UT205 exclusively induced the expression of the P2RX7 gene, which with other genes such as CFLAR and BIRC3, showed enrichment in processes of cell death by necrosis and necroptosis." (PMID 32391286, 2020). "We hypothesize that the inhibition of expression of Birc3 and cIAP1 by ECTV at 18 hpi, which was observed after cell stimulation with poly(I:C) or IFN-γ + LPS, may induce apoptosis at later stages of infection." (PMID 33020446, 2020). "We could, for example, verify that expression of IL10 or SOCS3 genes is reduced during the infection or that expression of STAT4, LAMP3, ADORA2A and BIRC3 genes peaks 6 h pi." (PMID 32070192, 2020). "Infection of AGS cells with H. pylori for 1 h dramatically increased the expression of BIRC3 (gene of cIAP2), but not the expression of BIRC2 (gene of cIAP1), BIRC4 (gene of XIAP), BIRC5 (gene of Survivin) and other apoptosis related genes." (PMID 32820150, 2020). "Interestingly, DVG-mediated upregulation of TNFR2 signaling was controlled by MAVS, as MAVS KO cells showed impaired upregulation of surface TNFR2 expression and blunted expression of the pro-survival genes TRAF1, BIRC3, and TNFAIP3 upon infection with SeV HD." (PMID 28986577, 2017). "Finally, NBD peptide delivery prior to VLP infection blocked Vpr WT and H71R-mediated BIRC3 and CXCL8 transcriptional activation, but not Vpr-induced DNA damage in primary human MDMs." (PMID 39269169, 2024).
inflammation (2 papers, 2022 to 2025). Aberrant reaction of the microcirculation characterized by movement of fluid and leukocytes from the blood into extravascular tissues. "This suggests that the Birc3 gene may be a key factor in LPS-induced liver inflammation and damage." (PMID 40243536, 2025). "Besides, the correlations between BIRC3 expression and asthmatic eosinophilic/allergic inflammation indicators (FeNO, IgE, and EOS%), pulmonary function (FEV1, FEV1% pred, FVC% pred, and FEV1/FVC), and inflammatory cytokines (IL-4, IL-5, IL-13, IL-25, IL-10, IL-33, and TSLP) were analyzed." (PMID 35287655, 2022).
neurodegenerative disease (1 paper, 2022). A disorder of the central nervous system characterized by gradual and progressive loss of neural tissue and neurologic function. "Hence, identifying the roles of BIRC3 in neurodegenerative diseases is of vital importance." (PMID 35783533, 2022). "However, the roles of BIRC3 in neurodegenerative diseases are still unclear." (PMID 35783533, 2022).
neurologic disorders (1 paper, 2016). "In conclusion, based upon the results of our comprehensive analysis of HHV-6A infected HA1800 cells, we revealed several genes correlated with neurologic disorders, especially CTSS, PTX3, CHI3L1, Mx1, CXCL16, BIRC3, and BST2 genes." (PMID 27344170, 2016).
BIRC3 also shares sentences with these, for which no sentence is quoted: B-cell lymphomas (6 papers); non-small cell lung carcinoma (6); diffuse large B-cell lymphoma (4); gastric MALT lymphoma (4); head and neck cancer (4); head and neck squamous cell carcinoma (4); prostate tumor (4); acute myeloid leukemia (3); adenocarcinoma (3); gallbladder cancer (3); medulloblastoma (3); rhabdomyosarcoma (3); Barrett esophagus (2); brain tumor (2); Burkitt lymphoma (2); Cerebral ischemia (2); chronic kidney disease (2); Crohn disease (2); Diabetes (2); esophageal squamous cell carcinoma (2); Fanconi anemia (2); HCMV infection (2); heart failure (2); hematologic malignancies (2); Hodgkins lymphoma (2); immune diseases (2); liver cirrhosis (2); lung squamous cell carcinoma (2); myocardial infarction (2); renal cell carcinoma (2).
A further 80 diseases each share a sentence with BIRC3 in 2 papers or fewer.